IL1B (interleukin 1 beta)
Diseases named in the same sentence as IL1B in open-access papers (continued):
Sharing a sentence is not in itself a finding about the gene and the disease.
Cerebral ischemia (continued). "In the brains of ASK1-deficient mice, decreased activation of microglia and reduced levels of TNFα, IL-6, and IL-1β were observed following brain ischemia." (PMID 39008037, 2024). "In contrast to our results regarding pro-inflammatory cytokines in the circulation, we found that cerebral ischemia significantly up-regulated the expression of IL-1β, TNF-α, and IL-6 mRNA in cortical tissue." (PMID 38102677, 2023). "The mRNA expression of M1-related proinflammatory mediators, including IL-6, IL-1β and iNOS, was obviously and progressively increased after cerebral ischemia, reaching a peak at 24 h." (PMID 37789455, 2023). "IL-1β has been therefore qualified as both beneficial and deleterious in cerebral ischemia depending on its plasma levels." (PMID 36969226, 2023). "All the patients had venous blood collected at admission and 7 days after the onset of the cerebral ischemia in order to determine the plasma concentration of interleukin-1 beta." (PMID 37893508, 2023). "ROS, NLRP3, Caspase-1, and IL-1β expression increased after cerebral ischemia, and this was reversed by HS treatment." (PMID 37371417, 2023). "Sal B significantly attenuated the protein expression of TLR4, p‐p38MAPK, p‐JNK, and IL‐1β compared with the tMCAO group at 24 and 72 h after cerebral ischemia (p < .05 for all)." (PMID 37904689, 2023). "Brain ischemia and reperfusion increased IL-1β and IL-6 in the blood of young mice and IL-17, IL-1β, and IL6 in the blood of old mice." (PMID 37697393, 2023). "Studies have shown that the expression levels of TNF-α, IL-1β, and other inflammation-related factors peak after 3 days of ischemic encephalopathy." (PMID 36855153, 2023). "Our results showed that IL-1β and IL-6 were increased in the blood of mice with brain ischemia and that valeric acid enhanced this increase." (PMID 37697393, 2023). "TNF-α and IL-1β are classical inflammatory cytokines after cerebral ischemia, while IL-4 and IL-10 are anti-inflammatory cytokines." (PMID 35496902, 2022). "CPB triggers cerebral ischemia and hypoxia and inflammation, increasing release of inflammatory factors such as IL-1β, IL-6, TNF-α." (PMID 35526011, 2022). "In the early stage of inflammation, white blood cells can be activated to release toxic oxygen metabolites, among which TNF-α and IL-1β are closely related to cerebral ischemia injury." (PMID 35664672, 2022). "MIAT can act as an endogenous competing RNA to negatively regulate microRNA-874-3p to reduce the level of pro-inflammatory factor IL-1β and reduce the neuroinflammatory response induced by cerebral ischemia/reperfusion." (PMID 36275741, 2022). "Our results confirmed that the levels of IL-1β and IL-18 were significantly upregulated after cerebral ischemia." (PMID 35690810, 2022). "The most important cytokines related to inflammation in cerebral ischemia include IL-1β, TNF-α, IL-6, IL-10, and transforming growth factor-β (TGF-β)." (PMID 35656190, 2022). "There was an increase in MCP1, IL-1β and IL-6 in the spleen of wild-type mice and fpr1-/- mice and IL-1β and IL-6 in the brain of wild-type mice after brain ischemia." (PMID 35547761, 2022). "After brain ischemia, levels of the pro-inflammatory IL-1β and TNF-α were elevated in the MCAo + vehicle group (155% and 187% of sham control levels, respectively), whereas anti-inflammatory IL-10 levels were not significantly changed (88% of sham values)." (PMID 35631536, 2022). "IL-1β, caspase-1, and inflammasomes have been reported to play important roles in cerebral ischemia reperfusion injury." (PMID 33747105, 2021). "Cerebral ischemia induction resulted in a huge increase in the levels of TNFɑ and IL-1β protein in the hippocampus (P<0.01)." (PMID 33643574, 2021). "The expression of IL-1 was upregulated after cerebral ischemia, especially IL-1β, which is a crucial factor involved in the inflammatory response, which can further activate microglia and aggravate ischemic injury." (PMID 34867201, 2021).
Cerebral ischemia (continued). "It was found that SIRT1 inhibited the activation of NLRP3 and the secretion of IL-1β in cerebral ischemia." (PMID 34039367, 2021). "All kinds of borneol significantly reduce TNF-α levels, while D-borneol and DL-borneol reduce IL-1β levels and DL-borneol reduces IL-6 in cerebral ischemia/reperfusion models." (PMID 34017247, 2021). "αCD147 (an anti-CD147 antibody) suppressed the splenic inflammatory response induced by cerebral ischemia, as evidenced by a decrease in splenic cytokine (TNFα, IL-6, IL-1β) and MCP-1 expression at 4h and 24 h after ischemia." (PMID 34975893, 2021). "Inflammation is the main pathogenesis for cerebral ischemia, and a marked inflammatory reaction is evoked by cerebral I/R with increased pro-inflammatory factors, such as TNFα, IL-1β, and IL-6." (PMID 34591125, 2021). "BTK is a tyrosine kinase that participates in the activation of the NLRP3 inflammasome, which in turn leads to the activation of caspase-1 and the production of mature IL-1β in the process of cerebral ischemia." (PMID 35008558, 2021). "The brain-related pathways demonstrated that PKall, KNG, B2KR, IL-6, TNF-α, IL-1β, LGALS-3, and PAR 2 were linked to superoxide anion generation and brain ischemia." (PMID 34867349, 2021). "The levels of TNF-α and IL-1β in the electroacupuncture group were lower than those in the model group 2 h and 1 d after cerebral ischemia (P < 0.05)." (PMID 32922507, 2020). "When microglial cells were activated after cerebral ischemia, the levels of NF-κB p65 and the expression of IL-1β and TNF-α, which are mediated by NF-κB p65, gradually increased, and the dynamic changes were generally temporally consistent." (PMID 32922507, 2020). "The pathogenic role of LPA1 in cerebral ischemia was associated with NLRP3 inflammasome activation, including NLRP3 upregulation, ASC speck formation, caspase-1 activation, and IL-1β maturation in a post-ischemic brain." (PMID 33202644, 2020). "Three days after cerebral ischemia, electroacupuncture obviously decreased the levels of IL-1β (P < 0.01); however, it had little effect on TNF-α expression (P > 0.05)." (PMID 32922507, 2020). "To determine the effect of QNDP on pro-inflammatory cytokines after cerebral ischemia in rats, we detected the mRNA levels of IL-1β, IL-18 in the ischemic cortex by real time PCR." (PMID 32153398, 2020). "It is known that cerebral ischemia leads to an activation of the inflammasome complex in microglia which results in maturation and secretion of IL-1β." (PMID 32382778, 2020). "At present, little research on the relationship between IL-18 and cerebral ischemia has been conducted, but it is considered to be a pro-inflammatory cytokine similar in structure to IL-1β." (PMID 32194375, 2020). "Following cerebral ischemia, IL-1β can turn on the nuclear factor (NF)-κB through the stimulation of TLRs, after this process it can activate the part of genome correlated with chemokines, cytokines, and other factors with a proinflammatory role." (PMID 32899616, 2020). "After cerebral ischemia, the expression of microglial markers (Iba-1 and CD11b) increased, and NF-κB p65, IL-1β, and TNF-α expression gradually increased." (PMID 32922507, 2020). "The pro-inflammatory cytokine IL-1β has been shown potentiate the actions of bradykinin and to increase microvascular permeability and edema formation after experimental cerebral ischemia reperfusion injury." (PMID 33327440, 2020). "FTY720 exerts neuroprotective effects in the simulated cerebral ischemia in vitro by reducing the release of IL‐1β." (PMID 32525289, 2020). "Following a 20-min transient global cerebral ischemia in rats, IL-1β mRNA and protein expression were increased not only during early reperfusion (1 h), but also at later times (6–24 h), indicating biphasic expression." (PMID 32264971, 2020). "Our previous study demonstrated that HS can inhibit microglia‐derived IL‐1β in focal brain ischemia in rats." (PMID 32529750, 2020).
Cerebral ischemia (continued). "Previous studies in this brain ischemia model have shown activation of astrocytes with overexpressed cytokines IL-1β or IL-6." (PMID 32501292, 2020). "A preceding study has indicated that the pro-inflammatory cytokines TNF-α and IL-1β were significantly downregulated in brain ischemia and microglia by the overexpression of Hsp70." (PMID 32899721, 2020). "Multiple LPS injections also dampened acute IL-1β production in a brain ischemia model, which correlated to reduced microglial activation and improved neuronal survival." (PMID 33208151, 2020). "Upregulated IL‐1β protein expression induced by brain ischemia can induce BBB permeability and aggravate neural injury." (PMID 32529750, 2020). "Cerebral ischemia-induced up-regulation of inflammatory cytokines such as TNFα and IL-1β are known to stimulate the expression of MMPs that can digest tight junction and basement membrane proteins, and thus contribute to BBB disruption." (PMID 31261992, 2019). "In this study, we demonstrated that cerebral ischemia-reperfusion injury caused elevated levels of TNF-α, IL-1β, and IL-6 in the serum." (PMID 31031621, 2019). "As one of the most important proinflammatory factors, IL-1β aggravates the progress of cerebral ischemia-reperfusion injury and type 2 diabetes." (PMID 29853850, 2018). "Systemic infusion of anti-IL-1β monoclonal antibody after cerebral ischemia insult attenuates the increase of IL-1β after ischemic incidence and BBB permeability." (PMID 29786644, 2018). "Some evidence suggests that CD44 is involved in exacerbating cerebral ischemia possibly through the production of the pro-inflammatory cytokine IL-1β, with CD44-deficient mice significantly protected from cerebral ischemia and reduced levels of IL-1β." (PMID 29519253, 2018). "Following cerebral ischemia, the expression of inflammatory cytokines such as interleukin-1 beta (IL-1β), tumor necrosis factor-alpha (TNF-α), and IL-6 are elevated." (PMID 28645333, 2017). "Our previous study suggested that HS can suppress the release of inflammatory mediators TNF-α and IL-1β in activated microglia and reduce the infarct size and brain water content following cerebral ischemia." (PMID 28288585, 2017). "ERβ stimulation decreased cellular inflammasome activity and IL-1β expression after global cerebral ischemia in ovariectomized rats." (PMID 28969701, 2017). "NF-κB is involved in the inflammatory responses that potentiate cerebral ischemic damage, thus activating many genes involved in the pathogenesis of cerebral ischemia, such as iNOS, IL-1β, TNF-α, ICAM-1, COX-2, and IL-6." (PMID 29220411, 2017). "Table I shows that cerebral ischemia/reperfusion significantly increased the levels of IL-1β and IL-10 in the serum." (PMID 25815894, 2015). "Both TNF-α and IL-1β cytokines are supposed to play crucial roles in inflammatory cells infiltration and glia activation induced by cerebral ischemia, which exacerbate cerebral ischemia-reperfusion injury." (PMID 24707308, 2014). "TNF-α also has been shown to be upregulated after cerebral ischemia with similar expression patterns as IL-1β." (PMID 25424430, 2014). "These actions of TNF-α and IL-1β providea central role in leukocyte infiltration and tissue injury after cerebral ischemia." (PMID 24946684, 2014). "For example, activated microglia following cerebral ischemia express a variety of proinflammatory cytokines including interleukin-1β (IL-1β), interleukin-6 (IL-6) and tumor necrosis factor-α (TNF-α), which induce neuroinflammation and neurotoxicity." (PMID 23912236, 2013). "Inflammation plays a crucial role in the pathophysiology of cerebral ischemia by producing inflammatory mediators, such as IL-1β, TNF-α, PGE2, NO, COX-2, and iNOS, which are important mediators implicated in the pathology of the ischemic brain." (PMID 23762140, 2013). "The presence of neuroinflammation during early brain ischemia was also confirmed in our study by elevated expression of inflammatory mediator-cytokine IL-1β." (PMID 24324296, 2013).
Cerebral ischemia (continued). "In another study increased production of IL-1β was reported even at 3–6 hours after induction of brain ischemia." (PMID 24324296, 2013). "It is suggested that the protective effect of GZFLC on rat brain ischemia-reperfusion injury is partly due to its inhibition of proinflammatory cytokines IL-1β and TNFα and upregulated expressions of anti-inflammatory cytokines IL-10." (PMID 23818926, 2013). "GW0742 administration i.c.v. dose-dependently inhibited the increase of TNF-α, IL-1β, and IL-6 and the reduction of IL-10 in hippocampus of cerebral ischemia-reperfusion rat." (PMID 23056034, 2012). "The proinflammatory cytokines TNFα, IL-6 and IL-1β have been found in the brain infarct region and the same cytokines have been suggested to be involved in the development of late cerebral ischemia after SAH." (PMID 23259581, 2012). "IL-1β and IL-1α levels were undetectable in IL-1α/β KO mice and IL-1α displayed a significant increase after cerebral ischemia in the ipsilateral hemisphere (two-way ANOVA followed by Bonferroni’s post hoc test, P < −0.05, not shown)." (PMID 23024646, 2012). "Rcan1-4 mRNA expression in the same brain ischemia model was determined by real time qRT-PCR, together with the mRNA expression levels of the proinflammatory cytokines IL-1β, TNFα and interleukin 6 (IL-6) and the proinflammatory gene cyclo-oxygenase 2 (Cox-2)." (PMID 22397398, 2012). "IL-1β mRNA is detected within 3-6 h after cerebral ischemia, although there is very little direct evidence that IL-1β protein is produced, and almost no information is available about IL-1α." (PMID 22206506, 2011). "In order to determine this we investigated the temporal and spatial profiles of IL-1α and IL-1β expression after cerebral ischemia." (PMID 22206506, 2011). "Antibodies that neutralize IL-1β or TNF-α, the soluble form of IL-1β or TNF-α receptor, and IL-1β analogue all function to reduce the injury caused by brain ischemia in rodents." (PMID 21696573, 2011). "In the studies of heat stroke, systemic treatment with DXM attenuated serum IL-1β levels and cerebral ischemia damage, and improved survival in heat stroke." (PMID 20937119, 2010). "Thiscellular staining pattern is in line with previous studies infocal brain ischemia identifying ramified microglia as a majorsource of IL-1β under pathological conditions." (PMID 16864909, 2006). "Following cerebral ischemia, immune cells, including microglia, undergo activation, transitioning from the M2 to the M1 phenotype, which leads to the production of pro-inflammatory cytokines such as IL-1β, IL-6, TNF-α, and chemokines." (PMID 40365317, 2025). "In conclusion, downregulation of PHGDH in astrocytes post cerebral ischemia-reperfusion predominantly drives astrocyte pyroptosis via oxidative stress, resulting in the release of pro-inflammatory cytokines (e.g., IL-1β and IL-18) and subsequent exacerbation of ischemia-reperfusion injury." (PMID 41344159, 2025). "A single dose of LGU (0.72, 2.16 mg/kg) could significantly reduce the contents of TNF-α and IL-1β in the infarction-side brain tissue of the cerebral ischemia/reperfusion injury model." (PMID 38927572, 2024). "However, inhibiting other proinflammatory genes, such as NF‐κB, MAPK, and IL‐1β, can also reduce cerebral ischemia reperfusion injury in animals." (PMID 37789643, 2024). "The assembly of the inflammasome is also a key part of the pyroptotic pathway during cerebral ischemia, and the upregulation of the NLRP3 inflammasome complex, as well as IL-1β and IL-18, has been demonstrated in the brain tissue of patients with cerebral ischemia." (PMID 37373274, 2023). "For instance, up-regulation of IL-1R2 in microglial cells and brain endothelial cells attenuated central nervous system (CNS) inflammation in experimental models of IL-1β-induced-neurotoxicity (e.g. central administration of IL-1β, kainic acid administration, cerebral ischemia)." (PMID 35211118, 2022).
Cerebral ischemia (continued). "Similarly, in rat models of cerebral ischemia, triflusal conferred a prominent neuroprotective effect through the inhibition of glial activation and suppression of NF-κB-regulated expression of IL-1β, TNF-α and COX-2." (PMID 35631487, 2022). "Interestingly, miR-124 upregulation plays a protective role in cerebral ischemia–reperfusion injury by restricting pyroptosis as evidenced by the limited expressions of IL‐1β, IL‐18, Caspase-1, and GSDMD." (PMID 36243708, 2022). "Besides, the systemic infusion of IL-1β neutralizing antibodies reduced short-term brain injury after cerebral ischemia in the ovine foetus." (PMID 33757539, 2021). "The results indicated that the inflammatory cytokines TNF‐α, TGF‐β, IL‐6, and IL‐1β were involved in the pathological injury process of cerebral ischemia, whereas casticin could significantly reduce their expression and the damage to brain cells." (PMID 33704926, 2021). "More and more studies have shown that a variety of inflammatory cytokines, such as TNF-α, IL-1β, and IL-6, are released after cerebral ischemia, which can transform ischemic injury into inflammatory injury and promote the apoptosis and necrosis of nerve cells and the formation of brain edema." (PMID 34447315, 2021). "Treatment with melatonin could suppress the levels of IL-6, TNF-α, and IL-1β in animal models of brain ischemia/reperfusion injury, subarachnoid hemorrhage, and traumatic brain injury." (PMID 34685627, 2021). "In our present study, QNDP could reduce the expression of NLRP3, cleaved caspase-1, IL-1β, and IL-18, alleviate brain edema, and improve the neurological function after cerebral ischemia." (PMID 32153398, 2020). "Moreover, the release of bradykinin and IL-1β contribute to reactive oxygen species generation in the early stages of cerebral ischemia and reperfusion injury." (PMID 33327440, 2020). "Similarly, in the rat brain with cerebral ischemia, pioglitazone (a PPARγ agonist) reduced the level of IL-1β but upregulated IL-1Ra." (PMID 31691186, 2020). "Studies have shown that Cel can reduce focal cerebral ischemia‐reperfusion injury in rats, and the underlying mechanism may involve the inhibition of NF‐κB activation, the expression of TNF‐α and IL‐1β, and the subsequent reduction of inflammation." (PMID 33282271, 2020). "In addition, we found that cerebral ischemia resulted in remarkably increased mRNA expression of interleukin (IL)-1β in both male and female mice, which were consistently reversed by PRAP-1 inhibition." (PMID 32317937, 2020). "Therefore, suppressing the TNF-α and IL-1β expression is effective for inhibiting cell death following cerebral ischemia." (PMID 32742603, 2020). "Cerebral ischemia and abnormal glucose level can both activate inflammasome and recruit simultaneously a variety of immune cells which mediate the activation of proinflammatory cytokine caspase-1 and IL-1β." (PMID 29853850, 2018). "To investigate whether adjudin-pretreated NSCs in the acute phase of cerebral ischemia had a better effect on immunomodulatory influence, we first examined IL-6, IL-1β, and TNF-α mRNA expression in both the cortex and the striatum." (PMID 29115993, 2017). "IL-1β can be observed 2–6 h after cerebral ischemia and reaches a peak at 12–24 h." (PMID 28101118, 2016). "Whereas TNF-α and IL-1β appear to exacerbate cerebral injury, transforming growth factor-β and IL-10 may exert neuroprotective effects during cerebral ischemia reperfusion." (PMID 25092271, 2014). "TNF-α and interleukin 1beta (IL-1β) exert neurotoxicity in cerebral ischemia in the presence of elevated inducible nitric oxide synthase (iNOS), while in the absence of iNOS, both cytokines appear to contribute to neuroprotection and plasticity, highlighting the role of the context." (PMID 23691263, 2013). "Evidence suggests that pro-inflammatory cytokines such as IL-1β, IL-6 and TNFα may influence the extent of neuronal damage after cerebral ischemia." (PMID 22873409, 2012).